EGFR (epidermal growth factor receptor)
Diseases named in the same sentence as EGFR in open-access papers (continued):
Sharing a sentence is not in itself a finding about the gene and the disease.
cancer (continued). "Frequently, EGFR is elevated in different cancers and this high expression correlates positively with cancer progression and poor prognosis." (PMID 39888904, 2025). "By inhibiting the cleavage of EGFR ligands, the C12 mAb effectively suppresses EGFR phosphorylation in these cancer cell lines, highlighting its potential as a therapeutic agent." (PMID 41050403, 2025). "Clinical studies have demonstrated that EGFR is frequently overexpressed or aberrantly activated in multiple cancers, making it a crucial biomarker for cancer diagnosis and a major therapeutic target." (PMID 40906195, 2025). "The specificity of EGFR targeting and observed clinical benefits in cancer progression and metastasis highlight lapatinib as a promising therapeutic candidate 10-12." (PMID 40612670, 2025). "While less efficient than EGFR-TKIs in inhibiting the growth of EGFR mutant cancer cells, sorafenib and chemotherapy specifically target the emerging subpopulations of resistant cells, thus prolonging NSCLC response to EGFR-TKIs." (PMID 40846697, 2025). "Our findings from this study contribute to the growing body of evidence that EVs have a significant impact on cancer biology, specifically in relation to EGFR signaling." (PMID 40210802, 2025). "An overview of the role and current landscape of EGFR inhibitors in cancer treatment, with a particular emphasis on recent progress in the design, synthesis, and development of novel thiazole hybrid compounds as promising selective EGFR TKIs." (PMID 41488515, 2025). "We analyzed how EGFR expression impacted the overall survival of ESCC patients using the web tool from the University of Alabama at Birmingham cancer database (UALCAN)." (PMID 40722671, 2025). "TAMs also produce EGF which can increase cancer cell migration and invasion by binding to EGFR expressed on cancer cells." (PMID 40376304, 2025). "The epidermal growth factor receptor, or EGFR, is a tyrosine kinase receptor widely studied in cancer." (PMID 40432717, 2025). "Consistently, nanobody-drug conjugate selectively eliminates EGFR+ cancer cells, demonstrating a higher CDDP accumulation in cells via EGFR-mediated endocytosis than free cisplatin." (PMID 39940647, 2025). "Specifically, we examined the phosphorylation of nuclear factor kappa B (NF‐κB), a well‐known transcription factor involved in inflammation and cancer progression, which is activated downstream of EGFR." (PMID 40830825, 2025). "Several observations suggest that AGR2 plays a role in cancer progression, including its necessity for EGFR presentation at the cell surface, its upregulation in Estrogen Receptor-positive breast cancers, and its ability to transform colonic epithelial cells." (PMID 40867591, 2025). "EGFt facilitates drug delivery and inhibits the binding of native ligands to EGFR on cancer cells, thereby impeding cell proliferation and differentiation." (PMID 40428099, 2025). "Future studies should test novel anti-EGFR/HER2 therapies in KRASWT cancers further selected with a comprehensive molecular profile." (PMID 40507311, 2025). "In this context, herein, we have mapped the first step of the metabolite-cell signaling-gene regulatory circuit connecting ganglioside metabolism with cancer, controlled by the EGFR-mTORC2/RICTOR complex." (PMID 40934285, 2025). "The molecular architecture of acquired resistance to EGFR‐TKIs in other cancers, such as NSCLC, is well‐characterized and highly relevant." (PMID 41355397, 2025). "Cetuximab and Matuzumab, which target EGFR, have shown significant efficacy in treating cancers such as colorectal cancer as well as head and neck squamous cell carcinoma." (PMID 41583479, 2025). "Research has demonstrated that hsa-miR-486-3p regulates EGFR expression by inducing apoptosis, impacting cancer cell drug resistance." (PMID 40342975, 2025).
cancer (continued). "Genomic alterations in anaplastic lymphoma kinase (ALK) and c-ros oncogene 1 (ROS1) have been previously identified to be associated with a very high risk of VTE, whereas lower rates were reported for EGFR-mutated and ALK/ROS1/EGFR-wildtype cancers." (PMID 39858040, 2025). "Over the past few decades, there has been increasing interest in developing small molecules that target RTKs as potential therapies for various types of cancer, with a particular focus on EGFR in different cancer types." (PMID 40560045, 2025). "These interactions thus indicate that bioactive compounds in pomegranate peels attack and inhibit the P13/AKT and EGFR signaling pathway, suppressing the formation of cancer cells." (PMID 40573291, 2025). "EGF, a vital growth factor, binds to EGFR on cancer cells, activating MAPK/ERK and PI3K/AKT pathways, ultimately promoting PD‐L1 gene transcription." (PMID 39258533, 2025). "Recent reports by us and others suggest that CD109 promotes cancer progression by potentiating epidermal growth factor receptor (EGFR) signaling in SCC cells." (PMID 40317079, 2025). "By functionalizing the exosome surface with ligands that bind to receptors overexpressed on cancer cells, such as EGFR, HER2, or PSMA, these vesicles can home in on tumor sites with remarkable accuracy." (PMID 40843170, 2025). "EGFR is frequently expressed at elevated levels in various forms of cancer and its expression frequently correlates positively with cancer progression and poor prognosis." (PMID 40738059, 2025). "In a lung tumor-bearing mouse model, rLZ-8 was also shown to effectively inhibit cancer progression and reduce tumoral EGFR expression in vivo." (PMID 40733125, 2025). "This property is more beneficial for anti-cancer therapeutics than conventional EGFR inhibitors for minimal side effects." (PMID 41140511, 2025). "This study highlights the potential of Salicornia-derived phytochemicals as promising candidates for targeted cancer therapy through the inhibition of human epidermal growth factor receptors (HER1, HER2, and HER4)." (PMID 40728964, 2025). "Emodin potentiates the anti-cancer effects of EGFR inhibitor on pancreatic cancer (PANC-1 and BxPC-3) cells by inhibiting STAT3 signaling, promoting apoptosis." (PMID 40490812, 2025). "The correlation between EGFR expression and cancer prognosis was studied in a retrospective review of EGFR studies." (PMID 41226646, 2025). "Suppresses EGFR signaling, induces apoptosis via caspase-3 activation, inhibits cancer cell proliferation, migration, and invasion, and downregulates matrix metalloproteinases." (PMID 40918117, 2025). "This case underscores the complexity of managing NSCLC with coexisting EGFR and KRAS mutations and highlights the importance of continuous molecular monitoring to adapt treatment strategies as the cancer evolves." (PMID 39852181, 2025). "To test the functionality of our site‐specifically labeled EGF constructs, we used the human cancer cell line A549, stably expressing EGFR‐GFP." (PMID 40181613, 2025). "Through this action, omega-3 indirectly inhibits multiple pro-cancer signaling pathways, including the EGFR-mediated RAS/MAPK cascade and the PI3K/Akt survival pathway." (PMID 40808836, 2025). "Given the critical role of EGFR in cancer biology, targeting this receptor has emerged as a promising therapeutic strategy, particularly for patients diagnosed with HCC, in which EGFR overexpression or hyperactivation is frequently observed." (PMID 40656954, 2025). "Some 17β-estradiol derivates have been proven to be cytotoxic against various cancers including EGFR-dependent TNBC." (PMID 39942711, 2025). "For example, some options limit the scope of use to cancer types with the overexpression of EGFR, and most patients become resistant to therapy within a year of starting treatment, leading to severe side effects, including rashes." (PMID 40535810, 2025).
cancer (continued). "In cancer patients, TKIs are used to counteract the activity of hyperactive EGFR mutants, such as the common Leu858Arg substitution or exon 19 deletion." (PMID 39533106, 2025). "In this study, we developed an effective method for IT injection of EGFR‐targeted CRISPR LNPs (cLNPs) that knock out a cancer‐specific gene, SOX2." (PMID 39736115, 2025). "A range of other new molecules has shown dual EGFR/tubulin inhibition strategies to treat EGFR‐aberrant cancer." (PMID 41269051, 2025). "EGFR activation promotes resistance to radiotherapy while inhibition with antibody (i.e. cetuximab) radiosensitizes cancer cells." (PMID 40181161, 2025). "Cells exhibiting high expression of BCAN, GFAP, and EGFR were categorized as cancer cells, while endothelial cells displayed elevated levels of FLT1, CLDN5, and ABCG2." (PMID 41041071, 2025). "To further interrupt the cancer-promoting functions of Ephrin A1, we inhibited EGFR activation by EGFR tyrosine kinase inhibitor (TKI) erlotinib and then evaluated the function of Ephrin A1." (PMID 39838173, 2025). "The conjugation of EVs with EGFR-targeting peptides or anti-EGFR nanobodies facilitates their accumulation in EGFR-positive cancer cells both in vitro and in vivo." (PMID 40496863, 2025). "Stromal cells altered the expression of immunotherapeutic targets on cancer cells, such as epidermal growth factor receptor (EGFR), Cluster of Differentiation 47 (CD47) and Programmed death-ligand 1 (PD-L1)." (PMID 40376304, 2025). "Epidermal growth factor receptor (EGFR): mAbs such as cetuximab and panitumumab can block the EGFR, which is involved in the cell proliferation, growth, and metastasis of cancer cells." (PMID 40649207, 2025). "Quercetin and EGCG show promise as complementary cancer therapies by inhibiting EGFR signaling and modulating related pathways, which enhance the effectiveness of conventional EGFR‐targeting treatments like tyrosine kinase inhibitors and cetuximab." (PMID 40115248, 2025). "Mounting evidence highlights the critical interplay between the EGFR and Hh pathways in driving tumorigenesis and therapeutic resistance across multiple cancer types." (PMID 41214390, 2025). "Based on the present study, the inhibition of EGFR at an early stage of radiotherapy can inhibit the development of radioresistance in cancer cells." (PMID 40003899, 2025). "Previous studies have shown that anti-cancer immune responses were highly induced by NIR-PIT targeting EGFR, CD29, and CD44." (PMID 39751657, 2025). "The critical role of EGFR (ErbB1) activation in cell proliferation and differentiation explains its direct relationship with human cancer development." (PMID 39910656, 2025). "For cancer to be effectively treated, inhibitors that target both the active and inactive forms of EGFR protein conformations must be developed." (PMID 40344575, 2025). "The chaperonin CCT is being explored as a diagnostic and therapeutic target in many cancers, including GBM, owing to its involvement in key oncogenic signaling pathways such as Wnt, VEGF, EGFR, and PI3K/AKT/mTOR." (PMID 41516249, 2025). "EGFR, a well-known driver of cell proliferation, was downregulated, aligning with the reduced proliferative capacity of cancer cells after CEBPB knockdown." (PMID 41411347, 2025). "KEGG analysis revealed PI3K-Akt signaling, EGFR inhibitor resistance, and other cancer-related pathways." (PMID 40963691, 2025). "Cellular uptake in cancer cells was significantly increased, with EGFR-targeted NPs showing a 1.45-fold higher fluorescence intensity after 2 hours of incubation compared to non-targeted NPs." (PMID 40880603, 2025). "qRT-PCR analysis revealed that 4-TCPA treatment led to significant downregulation of VEGFR2 and EGFR across all three cancer cell lines." (PMID 40592982, 2025).
cancer (continued). "The targeting component: An anti-EGFR bispecific antibody is used to target the EDVs to cancer cells that express EGFR." (PMID 40227645, 2025). "Nanoparticle with a KSP siRNA and Pretubulysin, a microtubule targeting agent, resulted in increased anticancer activity in epidermal growth factor receptor (EGFR) overexpressing cancer cells when compared to both KSP siRNA and Pretubulysin alone." (PMID 41009541, 2025). "EGFR and its family members contribute to several complex signaling cascades, including growth, differentiation, adhesion, migration, and survival of cancer cells." (PMID 39780275, 2025). "EREG is a known ligand for the epidermal growth factor receptor (EGFR), and its overexpression has been implicated in promoting proliferation in various cancers." (PMID 40970086, 2025). "EGFR can modulate the composition and release of EVs, thereby affecting their ability to mediate communication between cancer cells and the surrounding stromal cells." (PMID 40210802, 2025). "FMD blocks cancer cell proliferation with EGFR-TKI, creating a synergistic anti-proliferation effect." (PMID 40808689, 2025). "Cancer-selective replication can be activated through epidermal growth factor receptor (EGFR)/Ras pathway signaling." (PMID 41296382, 2025). "Heterogeneity of the EGFR protein expression has been observed in clinical samples from multiple cancer types." (PMID 39940134, 2025). "expanding the landscape of potential EGFR inhibitors for EGFR-driven cancers, including non-small cell lung cancer (NSCLC), based on the validation and confirmation scores obtained from molecular docking simulations and molecular (MD) analysis." (PMID 41174103, 2025). "One example is that DNMT inhibitor, decitabine, can reverse the hypermethylation status of EGFR promoters in different cancer types by enhancing EGFR expression and reversing EGFR-TKI resistance." (PMID 40275403, 2025). "Taken together, these results demonstrate an effective, systemic EGFR-directed ligand-conjugated platform for cancer delivery." (PMID 40762837, 2025). "Previous studies stated that YY1 can contribute to angiogenesis and other hallmarks of cancer through the activation of epidermal growth factor receptor (EGFR) and human epidermal growth factor 2 (HER2)." (PMID 41081939, 2025). "Antibodies or receptor tyrosine kinase (RTKs) inhibitors that target VEGF, VEGFR, FGFR, EGFR, or other neoangiogenesis-related molecules represent a significant area of the researches in anti-cancer targeted therapies." (PMID 39948481, 2025). "To assess the specificity of interaction between K‐EGFRR and target or off‐target cells, we used cancer cell lines naturally expressing varying levels of EGFR." (PMID 40104837, 2025). "Further understanding of the molecular mechanisms of EGFR signaling is crucial in the treatment of cancers." (PMID 39838173, 2025). "In this study, CTX, a specific antibody drug for cancer that binds specifically to EGFR on the surface of cancer cells, was used to develop a radioimmunotherapy candidate." (PMID 40078313, 2025). "Here, we present the selection, engineering, and characterization of CaRAEGFR which is shown to have a conditional target affinity for EGFR-expressing cancer cells." (PMID 41289384, 2025). "These pathways include the EGFR tyrosine kinase inhibitor resistance signaling pathway, signaling pathways in cancer, insulin resistance signaling pathway, and chemical carcinogen–receptor activation signaling pathway, among others." (PMID 40733369, 2025). "In summary, cancer cells promote macrophage infiltration and M2 polarization and express specific molecules to evade macrophage phagocytosis through the EGFR signaling pathway." (PMID 40859900, 2025). "Among these shared targets, several key genes involved in cancer-related pathways were identified, including EGFR, PARP1, SRC, MET, GSK3B, and CYP19A1." (PMID 40963691, 2025).
cancer (continued). "It was shown that any dysregulation of these processes leads to cancer development, making therefore EGFR one of the main anticancer targets." (PMID 39940134, 2025). "Quinazolinone derivatives, showing promise as EGFR inhibitors with diverse biological activities, are under active investigation to enhance therapeutic specificity and efficacy against cancer." (PMID 40001513, 2025). "Recent studies have identified novel roles for EGFR in regulating autophagy and cellular metabolism, which are activated in response to environmental and cellular stresses in cancer cells." (PMID 40236691, 2025). "KEGG pathway examination suggested substantial enrichment in pathways encompassing pathways in cancer, PI3K/Akt signaling, EGFR tyrosine kinase inhibitor resistance, endocrine resistance, and central carbon metabolism in cancer." (PMID 40444042, 2025). "To further investigate the immune resistance of patients with high EGFR scores in pan-cancer, we developed EGFR.Sig based on the interactive analysis of 34 scRNA-Seq cohorts." (PMID 40574864, 2025). "Aberrant EGFR signaling drives cancer progression through the activation of downstream pathways, including RAS/RAF/MEK/ERK and PI3K/AKT, which enhance cell survival, invasion, and metastatic potential." (PMID 41419456, 2025). "Erlotinib suppresses the proliferation and metastasis of cancer cells by inhibiting EGFR activation and subsequently blocking downstream signaling pathways." (PMID 39836268, 2025). "Single‐antibody‐functionalized 177Lu‐AuNP interacted only with cells expressing the corresponding receptor (HER2 or EGFR), whereas dual‐antibody‐functionalized 177Lu‐AuNP interacted with cancer cells expressing HER2, EGFR, and both receptors." (PMID 40395357, 2025). "EGFR signaling activation plays an important role in inflammation-driven metaplasia and cancer initiation." (PMID 40308779, 2025). "EGF exerts its effects through binding to the EGF receptor (EGFR), and its signaling pathways play essential roles in cancer development and anti-cancer therapies." (PMID 40733034, 2025). "A key feature in cancer progression is the overactivation of the cell cycle mediated by EGFR signaling pathways such as PI3K/Akt/mTOR and RAS/RAF/MEK/ERK." (PMID 40943615, 2025). "Other relevant studies have been conducted conjugating anti-EGFR Nbs to different types of nanocarriers for cancer active targeting." (PMID 39940134, 2025). "As a recombinant chimeric immunoglobulin G1 (IgG1) monoclonal antibody and EGFR inhibitor, cetuximab inhibits EGFR overexpression in cancer cells." (PMID 40777125, 2025). "Several pathways connecting ganglioside metabolism to invasion, including receptor tyrosine kinase signalling, such as EGFR and PDGFR, which are frequently implicated in cancer invasion, have been reported." (PMID 39726234, 2025). "EGFR is a well-known regulator of PD-L1 expression in various cancers, particularly in non-small cell lung cancer (NSCLC)." (PMID 40507229, 2025). "EGFR, a member of the receptor tyrosine kinase family, plays a crucial role in various cellular processes and is regarded as a key target for cancer treatment." (PMID 40445424, 2025). "Kyoto Encyclopedia of Genes and Genomes (KEGG) pathway analysis further revealed significant alterations in metabolic pathways (e.g., lysine degradation), cancer-related pathways (e.g., EGFR inhibitor resistance), and cellular processes (e.g., iron death)." (PMID 41288727, 2025). "Overall, compound 6b showed promising anti-cancer activity via EGFR inhibition, apoptosis, and cell cycle arrest and is a good lead for further development as an EGFR-targeted agent." (PMID 40745188, 2025). "Its mechanisms of cancer inhibition include inhibiting tumor proliferation, growth, and neoangiogenesis by binding to cell-surface receptors like EGFR and Met, activating their pathways." (PMID 40109852, 2025).